IGF1 (insulin like growth factor 1)
Diseases named in the same sentence as IGF1 in open-access papers (continued):
Sharing a sentence is not in itself a finding about the gene and the disease.
ischemic stroke (continued). "Glutamate-induced excitotoxicity during brain injury in ischemic stroke and trauma leads to a significant increase in expression of IGF-1 in astrocytes, microglia, and neurons, followed by a significant stimulation of IGF-1R phosphorylation." (PMID 35203315, 2022). "Accumulated studies have explored gene polymorphisms and circulating levels of tumor necrosis factor (TNF)-α and insulin-like growth factor (IGF)-1 in the etiology of ischemic stroke (IS)." (PMID 35370618, 2022). "This approach allows for determination of the cellular mechanism(s) by which IGF-1 exerts its protective effects during ischemic stroke-induced stressors." (PMID 34887742, 2021). "Administration of exogenous IGF-1 reduces the extent of tissue damage and sensorimotor deficits in animal models of ischemic stroke, highlighting the critical role of IGF-1 as a regulator of neurovascular health." (PMID 34887742, 2021). "Preliminary experiments in our laboratory revealed that neuroprotection by IGF-1 in rats with ischemic stroke is accompanied by microglial changes and a decrease in neuroinflammation." (PMID 31920629, 2019). "IGF-1 has been used extensively as a potent neuroprotective agent in several animal models for ischemic stroke." (PMID 31920629, 2019). "We addressed the potential neuroprotective effects of systemic administration of IGF-1 in aged Wistar Han rats using the Et-1 model for the induction of ischemic stroke in conscious animals." (PMID 31920629, 2019). "The neuroprotective effect of IGF-1 in adult rats following ischemic stroke was paralleled by a decrease in Iba-1 positive pixels in regions I and V at the border of the infarct." (PMID 31920629, 2019). "It has also been suggested that in ischemic stroke patients, circulating IGF‐1 represents a marker of functional performance and outcome." (PMID 28961383, 2017). "In an in vitro experiment with brain endothelial cells IGF-1 reverted the hyperpermeability to bovine serum albumin induced by oxygen-glucose deprivation (an in vitro model of ischemic stroke)." (PMID 27738642, 2016). "The outcomes of this study reveal that physical exercise markedly induces IGF-1/Akt signaling activation after an ischemic stroke." (PMID 24945308, 2014). "Notably, besides pharmacologically improving microglial metabolic profiles, genetically enhancing Igf1 expression specifically in microglia also protects from ischemic stroke injuries." (PMID 38151703, 2024). "Emerging clinical research indicates a negative correlation between plasma IGF-1 concentrations and the risk of ischemic stroke." (PMID 40789569, 2024). "We first identified that upregulation of Igf1 was highly dependent on Trem2 both in vivo and in vitro, suggesting that Igf1 may serve as a potential downstream signal of Trem2 in ischemic stroke." (PMID 38151703, 2024). "Regulation of Igf1 can eventually exert effects on microglial metabolism, especially oxidative phosphorylation, which consequently affects microglial activities and alleviates ischemic stroke injuries." (PMID 38151703, 2024). "Mechanistically, Igf1 serves as one of the major down‐stream molecules of Trem2, and Trem2‐Igf1 signaling axis regulates microglial functional and metabolic profiles, exerting neuroprotective effects on ischemic stroke." (PMID 38151703, 2024). "IGF-1 was also found to regulate the survival and migration of bone marrow mesenchymal stem cells in an ischemic environment and improve neurological recovery after ischemic stroke." (PMID 36741282, 2023). "Moreover, it has been shown that systemic injections of IGF-1 improve neuronal health in hypertensive rat models with ischemic stroke." (PMID 36979670, 2023). "It suggests that IGF-1 may be a safe and potentially effective treatment for a variety of CNS disorders including ischemic stroke." (PMID 36741282, 2023).
ischemic stroke (continued). "Third, besides IGF-1, DPSC-CM contains the TIMP-1 and TIMP-2 which were associated with inhibition of matrix metalloproteinase (MMP) protein levels, thereby restoring BBB integrity and improving cerebral edema following ischemic stroke." (PMID 36181630, 2023). "This meta-analysis results demonstrated the association between serum IGF-1 levels and ischemic stroke in the Asian population not in the Caucasian population." (PMID 35370618, 2022). "Considering this, it is not surprising that IGF-1 has long-been implicated in the risk and severity of ischemic stroke." (PMID 34887742, 2021). "We show that IGF-1 reduced infarct size in aged rats with an ischemic stroke." (PMID 31920629, 2019). "The two type miRNAs together with IGF-1/IGFBP3 may contribute to the progression of ischemic stroke, which remains for further investigation." (PMID 30361294, 2018). "On the other hand, Robert and colleagues found that total IGF-1 levels did not predict risk of incident ischemic stroke." (PMID 30595648, 2018). "Moreover, further studies are required to clarify the neuroprotective mechanisms of IGF-1 in ischemic stroke process." (PMID 30595648, 2018). "In addition, IGF-1 is known to decrease the response of microglia to ischemic stroke and lipopolysaccharides." (PMID 26355725, 2015). "For example, recent research has shown that IGF-1 protects against ischemic stroke." (PMID 25278846, 2014). "However, comorbidities may affect the treatment efficacy in preclinical models, e.g., the neuroprotective effect of IGF-1 following ischemic stroke was impaired in hypertensive rats, compared to normotensive rats." (PMID 31920629, 2019). "Indeed, it has been suggested that IGF-1 may promote neuroprotection by acting on the blood-brain barrier; in an experimental model of ischemic stroke IGF-1 reduced the inflammatory infiltrate in the brain." (PMID 27738642, 2016). "We further demonstrated the therapeutic potentials of cyclocreatine in ischemic stroke, by enhancing microglial OXPHOS and facilitating its conversion from dystrophic microglia toward neuroprotective state, possibly via activation of Igf1." (PMID 38151703, 2024). "The strategy of microglial depletion and repopulation likely acts through depletion and repopulation of IGF1 and TREM2 positive microglial subpopulation, which serves as a potential therapeutic approach in ischemic stroke." (PMID 38151703, 2024). "Altogether, our study indicates that supplementation of cyclocreatine targeting microglial metabolism may be promising for therapeutic intervention in ischemic stroke, even in the absence of Trem2, the mechanisms of which is closely associated with regulation of Igf1 expression." (PMID 38151703, 2024). "Other studies have reported that IGF-1 reduced brain infarct volume and protected neurons via IGF-1R in the rat brain with ischemic stroke." (PMID 35883879, 2022). "In recent years, studies suggested ischemic stroke via several growth factors promotes neurogenesis, including FGF-2, IGF-1, BDNF, VEGF, and chemokines, including SDF-1, MCP-1." (PMID 35625017, 2022). "Ischemic stroke promotes neurogenesis by several growth factors including FGF-2, IGF-1, BDNF, VEGF, and chemokines including SDF-1 and MCP-1." (PMID 35035503, 2022). "In contrast to other biomarkers, such as VEGF, serum levels of IGF-1 were not significantly correlated with improvements in depressive symptoms either at baseline or after 3-weeks of rehabilitation after ischemic stroke." (PMID 40141202, 2025). "Additionally, M2 microglia produce trophic factors, such as insulin-like growth factor 1 (IGF-1), which promotes neuronal proliferation, differentiation, and maturation, contributing to central nervous system repair after ischemic stroke." (PMID 40746532, 2025).
ischemic stroke (continued). "Intriguingly, alternatively activated microglia serve as the source of IGF-1 (insulin like growth factor-1) in the subventricular zone (SVZ) and promote proliferation, differentiation and migration into the striatum after experimental ischemic stroke." (PMID 34572077, 2021). "Microglia-derived IGF-1 is essential for cortical neuronal survival, is neuroprotective after ischemic stroke, and is upregulated in the adult rat SVZ and striatal microglia after ischemic stroke." (PMID 31954397, 2020). "Although IGF-1 treatment significantly improved the NDS following ischemic stroke in adult rats, this score was not significantly improved in aged rats." (PMID 31920629, 2019). "Furthermore, administration of IGF-1 and FGF2 has been effective in preventing the ischemic stroke possibly promoting neuronal plasticity." (PMID 26355725, 2015). "Another limitation is the lack of biomarkers (such as IGF-1, vitamin D, and microRNAs), which could assist in understanding the relationship between ischemic stroke and estrogenic therapy." (PMID 40861918, 2025). "During acute stages of ischemic stroke, PSD patients showed lower IGF-1 serum levels than non-PSD patients." (PMID 40141202, 2025). "Therefore, the objective of this study was to determine the importance of low IGF1 and alterations in IGF1/IGF1R signaling for CVD in RA and to assess whether similarities exist in patients without RA afflicted by ischemic stroke." (PMID 31327319, 2019).
liver disease (66 papers, 2006 to 2026). "Insulin-like growth factor-1 deficiency, which has been associated with liver diseases of several etiologies, including ALD, contributes to impaired mineralization, osteoblast proliferation, and collagen synthesis in the bone matrix." (PMID 37856513, 2023). "Insulin like-growth-factor 1 is a major contributor to bone production, and thus, its loss in liver disease results in a decreased BMD." (PMID 31038324, 2019). "The normal decline in IGF-1 levels with age was attenuated in HIV/HCV co-infected individuals compared to those with HCV mono-infection, and slower IGF-1 decline was independently associated with liver disease progression." (PMID 28503671, 2017). "Linear regression with generalized estimating equations was used to determine whether IGF-1 decline over time was independently associated with liver disease progression." (PMID 28503671, 2017). "We measured insulin-like growth factor-1 (IGF-1) levels longitudinally in 553 injection drug users who had liver disease staging with transient elastography, and we found that the decline of IGF-1 over time was strongly associated with liver disease progression." (PMID 28503671, 2017). "The levels of IGF-1 decreased in patients with Child-Pugh class B (P<0.001), whereas they were not significantly different according to age, gender, and etiologies of underlying liver disease." (PMID 24595361, 2014). "Consistent with this, our findings indicate IGF-1 was markedly diminished in patients with liver cirrhosis with more severe liver disease and subsequently poorer survival outcomes, aligning with patterns identified in previous research." (PMID 39624154, 2025). "IGF1-induced insulin sensitization has been in rodent models of liver disease, including models of NAFLD and NASH, and has been demonstrated to have antifibrotic properties." (PMID 38469144, 2024). "IGF-1 is primarily synthesized in hepatocytes, and its levels are reduced in patients with advanced liver disease." (PMID 37780552, 2023). "Circulating IGF-1 is produced mainly in hepatocytes, and its level decreases with progression of liver disease." (PMID 36010307, 2022). "The mean IGF-1 and (25- OH D) values were significantly correlated with the severity of liver disease (p < 0.001)." (PMID 31864303, 2019). "We aimed to assess the nutritional status of children with CLD and to correlate the anthropometric indices with the severity of liver disease, liver function tests, insulin growth factor-1 (IGF-1) and 25-hydroxy vitamin D (25- OH D)." (PMID 31864303, 2019). "This was expected since, previously, it has been showed that diminished expression of IGF-1 is related to the progression of different liver diseases." (PMID 28740570, 2017). "In the early stages of hepatic disease, IGF-1 treatment induces cell regeneration and cytoprotection, and is also effective as an anti-inflammatory and antioxidant agent, resulting in a concomitant reduction in fibrosis (both fibrogenesis and fibrolysis)." (PMID 28472963, 2017). "Our findings also enriched our knowledge about the mechanism of IGF-1 on intestinal barrier and indicated IGF-1 to be a promising therapy for preventing bacterial translocation, reducing hepatocytic damages and attenuating portal hypertension." (PMID 26152281, 2015). "Our findings confirmed that IGF-1 was able to decrease portal hypertension by reducing portal vein endotoxin via regulating intestinal tight junction proteins." (PMID 26152281, 2015). "The aim of the present study was to demonstrate the relation between the IGF-1 levels and severity of liver disease according to Child- Pugh and Model for end stage liver diseases (MELD) Scores." (PMID 23599716, 2013). "Therefore, we should be cautious about the risk of fractures particularly in patients with advanced-stage liver disease who have low serum IGF-1 levels." (PMID 36010307, 2022). "The relationship between IGF-1 plasma levels and liver disease has also been investigated." (PMID 35305249, 2022).
liver disease (continued). "We examined serum IGF-1 levels over time in a cohort of HCV-infected individuals for whom liver disease progression was carefully measured and in whom we previously reported strong associations between HIV, aging, and liver disease." (PMID 28503671, 2017). "We tested the hypothesis that HIV promotes liver disease progression in people with HCV co-infection by altering the decline in IGF-1 levels." (PMID 28503671, 2017). "A further challenge in the present study was in deducing whether changes in IGF-1 decline were the cause or effect of HIV infection and liver disease." (PMID 28503671, 2017). "Notably, in the present study IGF-1 decline was independently associated with HIV status and liver disease." (PMID 28503671, 2017). "Therefore in this study, we decided to find the relation between IGF-1 and severity of liver disease according to the MELD and child-pugh criteria." (PMID 23599716, 2013). "Therefore, the present study suggests that the development of portal hypertension with LS ≥ 4 kPa in ACLD may also trigger a decrease in IGF-1, and these multiple factors may form the initial pathogenesis of muscle mass loss associated with liver disease." (PMID 38024081, 2023). "According to these findings, IGF-1 therapy may be of value for improving liver diseases." (PMID 31171766, 2019). "Through reducing plasma endotoxin level, IGF-1 could reduce portal hypertension." (PMID 26152281, 2015). "Insulin-like growth factor 1 (IGF-1) is among a multitude of growth factors, which exert pleiotropic effects in liver disease." (PMID 35054837, 2022). "Serum IGF-1 levels were determined by ELISA and evaluated according to baseline characteristics and over time by HIV status and liver disease progression." (PMID 28503671, 2017). "Additionally, some other growth factors (such as IGF-1) in PRP were reported to promote protein synthesis and increase serum albumin and total protein levels in some liver diseases or injuries." (PMID 37590313, 2023). "The nGHD population seems to present lower IGF-1 levels as well, without any relationship with liver disease." (PMID 35305249, 2022). "The IGF-1 decline, in turn, was associated with liver disease progression, although this association did not explain how HIV worsens liver disease." (PMID 28503671, 2017). "We examined whether HIV infection affects the expected decline in IGF-1 in persons with chronic hepatitis C virus (HCV) infection and if that alteration in IGF-1 decline contributes to the link between HIV, aging, and liver disease progression." (PMID 28503671, 2017). "Neither the etiology of liver disease nor the Child Pugh score correlated significantly with preoperative IGF-1 levels in our study." (PMID 26186540, 2015). "Our preliminary results demonstrate significant associations between IGF-1 expression and liver cirrhosis and survival after resection in patients with HCC, independent of their underlying liver disease." (PMID 25052889, 2014). "It is reported that IGF-1 promotes hepatocyte proliferation, differentiation, cell cycle progression, and prolonging survival, suggested that IGF-1 might repress cell premature aging and repair intrahepatic cells to ameliorate liver diseases." (PMID 31171766, 2019). "However, adding the decline of IGF-1 levels to the model did not significantly change the associations of age, HIV, and liver disease." (PMID 28503671, 2017).